PAK1 (p21 (RAC1) activated kinase 1)
Diseases named in the same sentence as PAK1 in open-access papers (continued):
Sharing a sentence is not in itself a finding about the gene and the disease.
bladder cancer (9 papers, 2010 to 2025). "On the other hand, a previous study of bladder cancer showed that high Pak1 expression was associated with a higher risk of recurrence, even in patients with low grade/stage tumors." (PMID 20426825, 2010). "The negative correlation between miR-145 levels and PAK1 protein expression in bladder cancer indicates that miR-145 inhibits bladder cancer cell invasion by targeting PAK1." (PMID 40689207, 2025). "Increased PAK1 activation has also been correlated with the histological grade and lymph node metastasis of bladder cancer." (PMID 37190165, 2023). "They predicted that PAK1 was a direct target of miR-145 using bioinformatics methods and confirmed that miR-145 levels were negatively correlated with PAK1 protein expression in bladder cancer through a luciferase activity assay of the 3′-untranslated region of PAK1 messenger RNA." (PMID 40689207, 2025). "In human bladder cancer, PAK1 expression was significantly higher than in human normal urothelial cells and normal bladder tissues, respectively, which was comparable to high histological grade, lymph node metastasis, and tumor size." (PMID 37190165, 2023).
glioma (9 papers, 2019 to 2025). A benign or malignant brain and spinal cord tumor that arises from glial cells (astrocytes, oligodendrocytes, ependymal cells). "Surprisingly, we found that high-grade gliomas contained higher levels of PAK1 protein, and samples with lower PAK1 levels were from low-grade gliomas." (PMID 36064705, 2022). "In the subnetworks, several kinases, such as ABL1, ACVR1, EPHA4, MAPK9, PAK1 and SRC, were commonly associated with glioma, cell migration and cell death/survival." (PMID 32392905, 2020). "Interestingly, Rac1 and its downstream effector PAK1 have been reported to be involved in the maintenance of glioma stem-like cells and tumorigenicity in human glioma." (PMID 36230732, 2022). "The difference of PAK2 protein in glioma samples is similar to that of PAK1." (PMID 36064705, 2022). "The results show that the increase of p-PAK1 levels was extremely important for the maintenance of the malignant behavior of GBM cells, which also explained why the expression of PAK1 in glioma and paracancerous tissues showed differentially higher expression of PAK1 in glial cells." (PMID 36064705, 2022). "Studies on PAKs in gliomas showed that PAK1 and PAK4 play an important role in the occurrence and development of GBM, and the abnormal activation of PAK1 is even more prominent." (PMID 36064705, 2022).
leukemia (9 papers, 2015 to 2025). A malignant (clonal) hematologic disorder, involving hematopoietic stem cells and characterized by the presence of primitive or atypical myeloid or lymphoid cells in the bone marrow and the blood. "PAK1-full and PAK1Δ15 can be distinguished at the transcript level and we performed the analysis both in leukemia cell lines and in primary cells." (PMID 33464167, 2021). "In BCR/ABL1+ leukaemia, PAK1 and PAK2 are upstream regulators of the transcription factor STAT5 – a key node for initiation and maintenance of disease." (PMID 28707321, 2017). "Although leukemia cells express both PAK1-full and PAK1Δ15, these PAK1 isoforms are less abundant in leukemia cell lines and in more primitive primary cells, indicating that leukemia stem cells may express less PAK1 than more differentiated cells." (PMID 33464167, 2021). "Moreover, we detected the expression of PAK1 and phosphorylated PAK1 at Ser144 (p-PAK1) in seven leukemia cell lines (THP1, Kasumi-1, U937, HL60, and KG1 are AML cell lines, K562 is a CML cell line, and Jurkat is a T-ALL cell line) by western blot analysis." (PMID 34307365, 2021). "In particular, cells with higher pPAK1 content were more sensitive to FRAX597-induced cell death, which indicates that PAK1 kinase activity might promote leukemia cell survival." (PMID 33464167, 2021). "Recently, the p21-activated kinase 1 (PAK1) has emerged as a potential therapeutic target in cancer, due to its key influence in a variety of oncogenic signaling pathways, including leukemia." (PMID 34307365, 2021). "The band pattern obtained from leukemia cells was similar to that from adherent cells: PAK2 antibody recognizes a dominant band at 60 kDa, whereas PAK1 is detected in several bands in the range from 64 to 67 kDa." (PMID 33464167, 2021). "The cross-talk between PAK1 and STAT5 signal transductions is extremely important for leukemia, and the cross-talk between Hippo/YAP and FAK/ILK/PAK1 cascades promotes cell cytoskeleton modulation in liver cancer." (PMID 33796531, 2021). "Human BMSC (HS-5) was utilized to mimic the leukemia bone marrow microenvironment (BMM) in vitro, and co-culture model was established to investigate the role of PAK1 in BMSC-mediated drug resistance." (PMID 34307365, 2021). "Remarkably, the crosstalk between PAK1 and STAT5 signaling is of great significance in the treatment and prognosis of leukemia." (PMID 32863957, 2020). "In addition, PAK inhibition by IPA3 in leukemia cell lines significantly lowered OCR, revealing roles for PAK1 and PAK2 in the metabolic regulation of both mitochondrial respiration and aerobic glycolysis." (PMID 37759961, 2023). "We have shown previously that leukemia cell binding to a fibronectin-coated surface is not markedly affected by inhibition of Src kinases, and the Src/PAK1 axis is thus probably not important in this process." (PMID 33464167, 2021). "Here, we studied the individual roles of PAK1 and PAK2 in BCR/ABL1+ leukaemia." (PMID 28707321, 2017). "In addition to regulating apoptosis, genetic ablation of PAK1 enhanced the survival of KIT D814V bearing mice in secondary transplants, indicating that targeting PAK1 inhibits the growth/survival of KIT D814V bearing leukemia initiating cell (LIC)." (PMID 26158763, 2015). "In line with this hypothesis, reduction of PAK1, but not of PAK2 levels by means of shRNA was previously reported to inhibit cell proliferation in leukemia cell lines." (PMID 33464167, 2021).
lymph node metastasis (9 papers, 2010 to 2025). "Increased PAK1 activity associated with lymphovascular invasion and lymph node metastasis in patients." (PMID 37190165, 2023). "Rac/PAK1 pathway activation has been associated with lymphovascular invasion and lymph node metastasis of upper urinary tract cancer." (PMID 37190165, 2023). "Overexpression of PAK1 was significantly associated with tumor location (p = 0.011), lymph node metastasis (p = 0.026) and patient survival (p = 0.032)." (PMID 26023713, 2015). "The numbers of cases showing PAK1 CN increase in primary tumours only, lymph node metastases only, or both were too low to give reliable prognostic information." (PMID 37368917, 2023). "Of the 123 cases with available lymph node metastases, only three cases had PAK1 CN ≥6 in both the primary tumour and the corresponding lymph node metastases." (PMID 37368917, 2023). "Fourteen of the 123 cases for which lymph node metastases were available had PAK1 CN ≥4 in the primary tumour." (PMID 37368917, 2023). "Increased PAK1 expression in cancer cells compared to normal bladder epithelial cells, and was also comparable to high histological grade, lymph node metastasis, and tumor size in patients." (PMID 37190165, 2023). "Alteration of PAK-1 expression has also been associated with hormone receptor-positive breast cancer cells and increased PAK-1 expression was associated with lymph node metastasis." (PMID 33321758, 2020). "The Pak1 expression rate in lymph node metastasis was 71 percent, which is significantly higher than in the group without metastasis (43%)." (PMID 23298303, 2014). "Rac1, Pak1 and Rock1 expression in the lymph node metastasis group (75, 71 and 66%) were significantly higher than in the group without metastasis (51, 43 and 41%)." (PMID 23298303, 2014). "Rac1 activity and Pak1 expression were higher in the primary tumors of patients with postoperative lymph node metastasis than in those of patients with bladder recurrence from the LVI(+) group, but not the LVI(-) group." (PMID 20426825, 2010). "Of these, 8 also had PAK1 CN ≥4 in the corresponding lymph node metastasis." (PMID 37368917, 2023). "However, it is unclear whether Rac1 and Pak1 play a similar role in lymph node metastasis and bladder recurrence." (PMID 20426825, 2010). "A high level of Rac1 activity and Pak1 protein expression in the primary tumor was related to poor differentiation (P < 0.05), muscle invasion (P < 0.01), LVI (P < 0.0001), and lymph node metastasis (P < 0.0001)." (PMID 20426825, 2010).
renal cell carcinoma (9 papers, 2013 to 2025). "These pathways included some already known phosphoproteins involved in renal cell carcinomas, such as PAK1, PAK2, and BRAF." (PMID 36997065, 2023). "Although alterations in PAK1 expression and activity have been detected in various human malignancies, its potential biological and clinical significance in renal cell carcinoma (RCC) remains obscure." (PMID 25675297, 2015). "PAK-1 mediated stem-like phenotype through NF-kB/IL6 activation in renal cell carcinoma." (PMID 31658701, 2019). "The renal cell carcinoma pathway included some already known phosphoproteins involved in RCC, such as PAK1, PAK2, and BRAF." (PMID 36997065, 2023). "Moreover, the PAK1 and PIK3R1 genes have a crucial role in cell migration and mobility in the KEGG renal cell carcinoma pathway, and both of them have been extracted by our pipeline as KIRC IC genes." (PMID 33712625, 2021).
liver cancer (8 papers, 2013 to 2023). An epithelial or non-epithelial malignant neoplasm that arises from the liver. "As we all know, hepatitis can cause liver cancer, while interestingly; PAK1 was confirmed to help HCV RNA replication through PI3K and ERK activation." (PMID 32863957, 2020). "PAK1 and PAK2 are overexpressed in breast and liver cancer, and promote the occurrence and development of tumors." (PMID 34307365, 2021). "Although Pak1 was up-regulated in tumor compared to normal samples, it is also observed in TCGA liver cancer datasets, and thus not in a Rufy3-specific manner." (PMID 30060537, 2018).
lymphoma (7 papers, 2013 to 2023). A malignant (clonal) proliferation of B- lymphocytes or T- lymphocytes which involves the lymph nodes, bone marrow and/or extranodal sites. "PAK1 has been reported to mediate drug resistance in lymphomas, and targeting PAK1 suppressed the proliferation of chronic myeloid leukemia cells." (PMID 37190165, 2023). "In lymphoma, gene expression profiling in the drugs treated with BKM120, BEZ235, and BGT226 (PI3K and PI3K/MTOR inhibitors) in a panel of 60 cells showed higher expression of PAK1 association with PI3K resistance." (PMID 36830998, 2023). "Increased PAK1 expression develops drug resistance in lymphoma patients." (PMID 37190165, 2023). "For example, PAK1 was reported to mediate the resistance to PI3 kinase inhibitors in lymphoma." (PMID 35811334, 2022). "Leukemia and lymphoma: In acute myeloid leukemia (AML), bone marrow stem cells (BMSCs) increase the expression of PAK1, resulting in the activation of ERK1/2 signaling to promote drug resistance through modulating the apoptotic pathway." (PMID 36830998, 2023). "Finally, in lymphoma, overexpression of PAK1 (p21-activated kinase 1) was shown to mediate resistance to PI3K inhibition." (PMID 26404259, 2015).
meningioma (7 papers, 2015 to 2024). A generally slow growing tumor attached to the dura mater. "In particular, we demonstrate that independent activation of SGK1 and PAK1 may be partly responsible for the mTORC1 activation in NF2-deficient meningioma cells (model)." (PMID 26219339, 2015). "Merlin-deficient meningioma cell lines demonstrate increased expression of PAK1 compared to normal arachnoid cap cells, and knocking down PAK1 expression using doxycycline-inducible shRNA or treatment with PAK1 inhibitors inhibited cell proliferation in vitro and tumor growth in xenograft models." (PMID 31652973, 2019). "Loss of PAK function, in particular the PAK1 isoform, is associated with slower growth of NF2-deficient meningioma and schwannoma cells and has been proposed as a plausible therapeutic target for these tumors." (PMID 39083549, 2024). "Reduction of Pak1 expression had a greater effect than reduction of Pak2 expression, with no net increase in BLI signal over a five-week period, suggesting that, of these two enzymes, Pak1 has a dominant role in the growth of meningioma." (PMID 25596744, 2015). "To investigate the significance of Pak1 and Pak2 in meningiomas, we used doxycycline-inducible short hairpin RNA (shRNA) to reduce Pak1 or Pak2 expression, respectively." (PMID 25596744, 2015). "We found that Pak1 and Pak2 were much more abundant than Pak3 in both meningioma and arachnoidal cells, as determined by immunoblot." (PMID 25596744, 2015). "Here, we show that Pak1 expression is positively correlated with the degree of malignancy in primary meningiomas." (PMID 25596744, 2015). "In addition, we found a marked increased in the expression level of Pak1 in meningioma cells comparing with arachnoid cells (t-test, P = 0.046)." (PMID 25596744, 2015). "Western blot analyses of the meningioma cell lines corroborated high levels of protein expression of PAK1 and phospho-PAK1 and absence of NF2 in CH157-MN." (PMID 28552950, 2017). "Since depletion of Pak1 by shRNA induced a partial G1 cell cycle arrest, we sought to determine whether the same phenomenon would be obtained in NF2−/− meningioma cells after treatment with small-molecule Pak inhibitors." (PMID 25596744, 2015). "Loss of TRAF7 in meningeal cells promoted the activity of CDC42 and the p21-activated kinase PAK1 and enhanced RAS activity and the upregulation of the MAPK cascade in meningioma cells, suggesting that these pathways might be important in TRAF7-mutated meningiomas." (PMID 38571886, 2024). "PAK1 inhibition also leads to attenuated mTORC1 but not mTORC2 signaling, suggesting that mTORC2/SGK1 and Rac1/PAK1 pathways are independently responsible for mTORC1 activation in NF2-deficient meningiomas." (PMID 26219339, 2015).
pancreatic ductal adenocarcinoma (7 papers, 2014 to 2025). An infiltrating adenocarcinoma that arises from the epithelial cells of the pancreas. "For example, in pancreatic ductal adenocarcinoma, inhibition of PAK1 increased intratumoral cytotoxic lymphocytes, augmenting cancer cell death." (PMID 40783411, 2025). "ATRA inhibited PAK1 in pancreatic ductal adenocarcinoma cells and enhanced the inhibition by gemcitabine of pancreatic ductal adenocarcinoma." (PMID 37537668, 2023). "The inhibition of PAK1 blocks the PSC-mediated immune evasion of pancreatic ductal adenocarcinoma (PDA) cells, while reducing the intrinsic and PSC-stimulated PD-L1 expression in PDA cells, which further sensitizes PDA cells to CD8+ T cells." (PMID 36230657, 2022). "In pancreatic ductal adenocarcinoma, PAK1 activation triggers the Wnt/β-catenin signaling cascade that is involved in resistance to Gemcitabine." (PMID 32863957, 2020). "In contrast, PAK1 was expressed in the tumour tissue, in which the pancreatic ductal adenocarcinomas cells stained positive." (PMID 26774265, 2016).
Parkinson disease (7 papers, 2013 to 2025). A progressive degenerative disorder of the central nervous system characterized by loss of dopamine producing neurons in the substantia nigra and the presence of Lewy bodies in the substantia nigra and locus coeruleus. "Previous investigations have in fact suggested the involvement of PAK1 in dopamine neuron loss and Parkinson's disease." (PMID 35932179, 2022). "Conversely, cell death was observed when the activity of Pak1 was downregulated in the 6-OHDA rat model of Parkinson disease." (PMID 31201651, 2019). "Our data suggest that the oxidative stress-induced down-regulation of PAK1 activity could be involved in the loss of mesencephalic DA neurons through modulation of neuronal death, suggesting a novel role of PAK1 as a molecular determinant and mechanisms in the pathogenesis of Parkinson’s disease." (PMID 27121078, 2016).
schwannoma (7 papers, 2011 to 2025). A benign, usually encapsulated slow growing tumor composed of Schwann cells. "Due to the cardiotoxicities associated with PAK2 inhibition, recent developments in PAK1-specific drugs have been of interest for Merlin-deficient schwannomas." (PMID 39083549, 2024). "Overexpression and activation of Pak1 has been detected in many cancers, including schwannomas [45,46; see review 36]." (PMID 21454924, 2011). "PAK1 is a known miR-7 target in breast and schwannoma tumors." (PMID 23115635, 2012). "In addition, PAK1 activity is upregulated in NF2 patient-derived schwannomas." (PMID 26219339, 2015). "Studies supporting a role for Pak1, EGFR, and Ack1 activation/overexpression in schwannoma growth, suggests alternative strategies and rationale for the development of new therapies for these tumors based on overexpression of miR-7 or inhibition of Ack1, Pak1, and EGFR pathways." (PMID 21454924, 2011). "Moreover, overexpression of miR-7 directly targeted and inhibited expression of Ack1, Pak1, and EGFR in schwannoma cells." (PMID 21454924, 2011). "Given the fact that schwannomas, as many other cancers, are not always responsive to anti-EGFR treatment, our study suggests that Pak1 and/or Ack1 may prove critical therapeutic targets for schwannomas." (PMID 21454924, 2011).
squamous cell carcinoma (7 papers, 2011 to 2025). A carcinoma arising from squamous epithelial cells. "The results of our immunohistochemical studies on NSCLC TMAs revealed significantly higher mean PAK1 immunostaining scores in squamous cell carcinoma than in adenocarcinoma tissue specimens." (PMID 33261184, 2020). "One study showed that Pak1 expression is increased 11.8-fold in squamous cell carcinoma tissue relative to matched normal tissue." (PMID 26555075, 2015). "PAK1 inhibition also promoted tumor cell apoptosis as either single-agent treatment (in the context of tumor cells with focal genomic amplification of PAK1) or as combination therapy with several targeted agents (in squamous cell carcinomas)." (PMID 21653999, 2011). "However, the occurrence of squamous cell carcinoma is driven by the PAK1/CREB signaling pathway, and the migration and invasion of it are driven by PAK1/LIMK1/cofilin." (PMID 36230657, 2022). "Since smoking is a well-known risk factor in squamous cell carcinomas, but not in adenocarcinomas, the relatively high PAK1 expression in squamous cell carcinoma in this study could be related to the possibility of enhanced PAK1 expression owing to smoking." (PMID 33261184, 2020). "The effect of IPA-3 (PAK1 inhibitor) plus auranofin (PKCι inhibitor) combination was evaluated by cell viability assay, colony formation and western blotting assay, using three types of NSCLC cell lines: EGFR or KRAS mutant adenocarcinoma and squamous cell carcinoma with PAK1 amplification." (PMID 31660987, 2019). "Furthermore, PAK1 was found to be overexpressed in mouse malignant squamous cell carcinoma (SCC)." (PMID 27765920, 2016).